CD4 (CD4 molecule)
Diseases named in the same sentence as CD4 in open-access papers (continued):
Sharing a sentence is not in itself a finding about the gene and the disease.
tumor (continued). "The CD8+ T and CD4+ T cells are the most abundant types of T lymphocytes in tumor microenvironments and capable of eliminating tumor cells, their differentiation into dysfunctional states may render them ineffective at responding to immunotherapy." (PMID 37744271, 2023). "A group of researchers from the Netherlands worked on vaccines containing TLR-ligands (TLR-L) that covalently bound to antigenic SLP, and successfully demonstrated their capacity to induce the antigen-specific CD8+ and CD4+ T cell responses required for anti-tumor effects in preclinical studies." (PMID 36992219, 2023). "Our results thus far suggest that tumor-specific CD4+ T cells may be more likely to recognize antigen presented by APCs than by tumor cells themselves." (PMID 36512410, 2023). "Overall, our results suggest that an increase in the CD4+/CD8+ ratio is associated with an increased immune response and may inhibit tumor progression." (PMID 37206348, 2023). "Furthermore, TISIDB was used to investigate the correlation between HLA-G expression and tumor-infiltrating lymphocytes (TILs), including activated CD4+ T cells, CD8+ T cells, MDSCs and Tregs." (PMID 37875821, 2023). "Likewise, the landscape of tumor-infiltrating CD8+ and CD4+ T cells is generally associated with the prognosis of BRCA patients." (PMID 36845750, 2023). "In the context of Chimeric Antigen Receptors (CAR) and Tumor-infiltrating lymphocytes (TIL) therapy, a study unveiled that the different intensities of CD26 expression identified three distinct human T CD4+ helper cells: regulatory, naive, and stem memory, with varying levels of anti-tumor activity." (PMID 37170241, 2023). "Our study revealed that inhibiting YAP expression could hinder tumor growth and macrophages M2‐type polarization, activate Treg cells, activate CD4+ and CD8+ T cells, and regulate the expression of YAP, STAT3, p‐STAT3, PD‐L1, VEGF, and VEGFR‐2." (PMID 37329188, 2023). "These cytotoxic CD4 T cells were sufficient to kill tumor cells in a MHCII-dependent manner." (PMID 37654482, 2023). "The decreased mRNA expression of FOPX3 and ROR-γt in tumor tissues may be related to the decrease of the total number of CD4+ T cells in tumor microenvironment." (PMID 36713833, 2023). "It is known that antigen-specific cytotoxic CD4+ T cells can be generated in the tumor milieu." (PMID 36869048, 2023). "Our data suggest that human Treg cells may suppress CD4-mediated tumor cell killing, consistent with previous reports delineating the interplay between Tregs and CD4 CTLs25,33." (PMID 37185301, 2023). "In contrast, activated CD4 + T cells and regulatory T cells were detected in the infiltrated tumor." (PMID 37434173, 2023). "further demonstrate that most anti-tumor immune cells such as CD8+ T cells, activated memory CD4+ T cells, follicular T helper cells, NK cells, M1 macrophages and neutrophils cells increase in the tumor microenvironment of MSI-high CRCs, but Treg cells significantly decrease." (PMID 37124519, 2023). "However, T cells also have pro-tumor activity; CD4+ T cells inhibit CD8+ T cells’ anticancer activity by producing IL-4 and -10, and Th17 cells produce IL-17, which promotes tumor growth." (PMID 37736898, 2023). "In vitro killing of MAGE-A4+ tumor cells by CD8+ afami-cel was significantly greater compared with CD4+ afami-cel (at 72 hours: median, 79.9% (range, 33.5−97.6%; n = 37) versus median, 6.6% (range, −8.7% to 52.9%; n = 35), respectively; P = 5.8 × 10−11 (paired Wilcoxon test))." (PMID 36624315, 2023). "Although we observed no impact of VSVΔ51+T-DM1 on the activation status of CD8+ T-cells in tumours, TdLN, or spleens, our analyses revealed an average 2-fold increase in activated CD44hi, CD25+, or CD69+ tumour-infiltrating CD4+ T-cells in the same treatment group, relative to PBS or monotherapies." (PMID 37153626, 2023).
tumor (continued). "Studies have also shown that a higher ratio of CD4+/CD8+ T-cells to PD-L1 tumor expression is an independent predictor of better 4-year OS of DLBCL patients treated with Standard of Care (SOC) chemotherapy of Rituximab, Cyclophosphamide, Doxorubicin, Vincristine, Prednisone (R-CHOP)." (PMID 37920162, 2023). "Naïve CD4+ T cells can be differentiated into four types, namely helper T cells (i.e., Th1, Th2, and Th17) and Tregs, which are involved in the tumor immune microenvironment, tumor immune escape, immune homeostasis, and antitumor immunity." (PMID 37317214, 2023). "Therefore, CD4+ T-cells inhibit tumor proliferation and tumor angiogenesis and also support anti-tumor function of myeloid cells." (PMID 37727790, 2023). "In addition, antibodies bind to tumor antigens and help macrophages and DCs to uptake, process, and present or cross-present them to CD4+ and CD8+ T-cells, respectively." (PMID 37835465, 2023). "Low expressors presented lower response rates to ICIs when compared to the high expressors (16.7%, vs. 60%); moreover, patients whose tumor tissue presented CD8+/CD4+ ratios lower than two showed lower response rates than patients whose tumor tissue presented a >2 ratio RR (13.3% vs. 43 to 50%)." (PMID 37835378, 2023). "Moreover, the proportion and absolute number of CD4+Tem significantly increased after tumor resection." (PMID 36925914, 2023). "We also investigated the relationship between ATP7A and tumor related immune cells and found that ATP7A is positively correlated with cancer associated fibroblast, Tregs, macrophages M1, macrophages M2, CD4+ T cells, CD8+ T cells and NK cells, but negatively correlated with T cell gamma delta." (PMID 37885090, 2023). "Besides, although a positive correlation between HMGB1 expression and CD4+ memory T cells (R = 0.195, P ˂ 0.01) was observed, the correlation coefficient of other tumor-infiltrating immune cells was insignificant." (PMID 36907982, 2023). "This study investigated differences in clinical and pathological parameters as well as differences in the tumor immune microenvironment by immunohistochemical examination of tumor infiltration of CD4+, CD8+, FoxP3+, and CD1a+ cells in SD and NSND OSCC patients." (PMID 37345025, 2023). "An immune cell infiltration analysis revealed that effector immune cells, such as naïve and memory B cells, CD8 and activated CD4 T cells, and activated NK cells were significantly enriched in the low-mRPS group, indicating that a strong local anti-tumor response was elicited." (PMID 37685980, 2023). "Additionally, the described HIS tumor model provides a valuable preclinical platform to interrogate human CD4 CTL biology and establish therapeutic strategies to enhance their differentiation and function." (PMID 37185301, 2023). "Protection by CLTCH129>Q-specific CD4+ T cells was also dependent on the frequency of these cells at the time of tumor challenge, as mice receiving either 1 × 106 or 3.3 × 105 cells before challenge had decreased rates of survival after inoculation of SCC VII-GFP/Luc cells." (PMID 37400675, 2023). "This points to an interesting observation that CD8+ Tregs infiltrate this tumour model more aggressively than the CD4+ Treg counterparts, and gives wider implications, since CD8+ Tregs have been previously demonstrated to have more potent tumour suppressive functions than CD4+ Tregs." (PMID 36319895, 2023). "By contrast, more LAG-3+ cells were found in the CD4 than in the CD8 T cells in the tumor." (PMID 37174080, 2023). "However, these samples observed different stromal and tumor enrichments for CD4+ T cells, cDC1s, and XCR1+CD163+ cells compared to CRC1." (PMID 37731497, 2023). "Less common immunosuppressive cell types in human HCC consist of B cell population expressing PD-1, Th17 cells, CD4+ T cells expressing CCR4 and CCR6, CD14+ DCs expressing CTLA-4 and PD-1, tumor-associated neutrophils, tumor-associated fibroblasts, and type-II T helper cells (Th2)." (PMID 36845131, 2023).
tumor (continued). "In addition, Studies have shown that cytotoxic CD8+ T cells and CD4+ helper T cells can target antigenic tumor cells and inhibit tumor cell growth." (PMID 36829489, 2023). "In mice, IL11 can inhibit the anti-tumor effect mediated by CD4+ T cells." (PMID 37274740, 2023). "In theory, dead tumor cells are typically immune-tolerant or non-immunogenic, and under ICD induction, DCCs recruit antigen-presenting cells (APCs) and effector CD4+ and CD8+ T cells by releasing tumor-associated antigens and cytokines through damage-associated molecular patterns (DAMPs)." (PMID 37346077, 2023). "Moreover, previous studies have shown that patients with tumor metastasis have decreased total T cells and CD4+ T cells in peripheral blood." (PMID 37792639, 2023). "We propose a model where an effective response to ICI is marked with CXCL13+ CD8 T cell-driven recruitment of highly diversified, CXCR5+ B cell clones whose subsequent (tumor) antigen presentation activities induce and sustain the activation of tumor-reactive CD4 Tfh and CD8 T cells." (PMID 37435085, 2023). "Additionally, we examined other immune-related cells in the tumor microenvironment, including CD4+ T-cells (Th1, Th17, and Treg) and CD163+ cells." (PMID 37790758, 2023). "Therefore, radiation-upregulated TAAs activate both CD8+ and Th1 CD4+ T cells in a poorly immunogenic tumor, which result in enhanced antitumor response to ICIs and vaccines." (PMID 37377970, 2023). "CD4+ T helper (Th1) cells from the patient were expanded and activated in vitro and then reinfused into the patient, resulting in significant tumor reduction and even tumor disappearance in some cases." (PMID 37112747, 2023). "The higher presence of motifs in TILs-CD4+ samples may be useful for selecting potential tumor-reactive clonotypes if, as described in other pathologies, slightly different CDR3 sequences with identical 3-4aa motifs can recognize the same pMHC." (PMID 37600765, 2023). "In addition to baseline CD4+ T cell counts, CVD and tumor were associated with poor immune reconstitution in aged Chinese HIV-1 infected patients." (PMID 37928477, 2023). "IFN-γ–mediated cytotoxicity may occur through either direct CD4+ tumor cell recognition or by APC presentation in the TME." (PMID 38063199, 2023). "When tumor growth, its tumor antigens can be recognized by lymphocytes, then the secretion of cytokines activate different kinds of immune cells to exhibit cancer inhibitory effects such as CD4 + and CD8 + T cells, B cells and so on." (PMID 38066499, 2023). "Interestingly, simultaneous PD-L1 blockade and CD4+ T cell depletion additively suppressed tumor growth, resulting in tumor regression, while CD8+ T cell depletion completely reversed the antitumor effects of anti-PD-L1 therapy." (PMID 36969495, 2023). "In contrast to CD8+ T cells, it remains unclear whether tumor cells can directly shape the metabolic features and regulate the functional differentiation of CD4+ T cells." (PMID 38062068, 2023). "CD4+ T cells can broadly differentiate into immune-promoting T helper (Th) subsets, as well as the highly immune suppressive CD4+ regulatory cells (Tregs) with counteracting roles in anti-tumour immunity." (PMID 36564565, 2023). "On the other hand, MHC II complexes present tumor antigens to CD4+ T cells." (PMID 37371815, 2023). "The combination of both nanoformulations transformed the ‘cold’ TME into a ‘hot’ one, supported by increased numbers of CD8+ T cells, CD4+ T cells, dendritic cells, IFN-γ, TNF-α, and IL-12 and reduced numbers of MDSCs, Tregs, tumor-associated macrophages (M2), IL-4, IL-6, and IL-10." (PMID 37600822, 2023). "These immunological changes in the blood of tumor-regressing mice may represent biomarkers to monitor effective anti-tumor CD4 CTL immunity in circulation." (PMID 37185301, 2023).
tumor (continued). "To further explore the interaction between HLA-DRhighCD206+ TAMs and CD4+ TILs in the tumor microenvironment of LSCC, we examined the localization of both types of cells on serial tumor tissue section using immunohistochemical (IHC) staining for HLA-DR, CD206 and CD4." (PMID 36864443, 2023). "In this study we found that CD4 produced a large amount of IL-10 in TLS of the tumor which suggests that CD4 may regulate B cell IgG4 production by up regulating the level of IL-10." (PMID 36891293, 2023). "However, inflammatory monocytes recruited by CCL2 can also differentiate into monocyte-derived dendritic cells, which can present antigens to CD8 + and CD4 + T cells, thus assisting and stimulating the adaptive anti-tumor immune response." (PMID 36451019, 2023). "However, dMMR/MSI-H tumors harbor a vast infiltration of CD8+ and CD4+ T cells as well as macrophages and are characterized by the presence of type I interferons in the tumor microenvironment (TME)." (PMID 37511431, 2023). "The reduction in tumor growth was partially due to increased IFN-γ from CD4+ T cells and IL-12p70." (PMID 37514190, 2023). "We further investigated the effect of ADCC enhancement of BAT6026 on the proportions of CD4+ T cells and Tregs in mouse tumor, and the results showed that these cells were significantly reduced in mice treated with BAT6026 compared to its cognate antibody with regular ADCC, BAT6026-wt." (PMID 37576888, 2023). "Furthermore, we noted that the proportions of tumor-reactive CD8 + and CD4 + FoxP3- T-cells were similar, except for MM, which had significantly fewer tumor-reactive CD4 + FoxP3- T-cells than in NSCLC." (PMID 38057799, 2023). "Interestingly, primary human lung apCAFs derived from ATII rather than cancer or mesothelial cells exhibit certain anti-tumor effects by directly activating T cell receptors (TCRs) in tumor-infiltrating CD4 + T cells and shielding them from apoptosis." (PMID 37723510, 2023). "Thus, secreted factors from TCF1-depleted CD4+ T cells directly induced PD-L1 expression in tumor cells." (PMID 36239683, 2023). "CD4+ T cells, as a major type of T cells, play crucial roles in the regulation of tumor immunity." (PMID 36646683, 2023). "Patients with intense CD4+ cell infiltration or weak CD20+ cell infiltration, as well as patients with high PD-L1 expression on tumor cells (≥1%), could be characterized by a higher risk of recurrence." (PMID 38067231, 2023). "Indeed, it has been shown that the ICT response correlates with dense tumour infiltration of T lymphocytes in advanced solid tumours, characterised mainly by high intratumor levels of CD4 and CD8 positive markers in histological sections." (PMID 37454231, 2023). "However, the CD4+FoxP3+ Tregs density around S15+ TAMs was significantly higher than that around S15+ tumor cells." (PMID 37674198, 2023). "Among many cytokines, irradiated B16 melanoma tumor cells expressing granulocyte-macrophage colony-stimulating factor (GM-CSF) could arouse potent, durable, and specific anti-tumor immunity, activating both CD4+ and CD8+ cells." (PMID 37691932, 2023). "Moreover, MET decreased tumor weight and volume in vivo and increased the ratio of CD4+ to CD8+ T cells." (PMID 37509632, 2023). "Additionally, studies have indicated that calmodulin-dependent kinase kinase 2 (CaMKK2) reduces the amplification of effector CD4 + T cells to limit the tumor penetrance of GBM patients." (PMID 37208656, 2023). "Furthermore, in the tumor microenvironment, Treg-dependent regulation of IL-2 was demonstrated to be critical for the acquisition of cytotoxic features by tumor-infiltrating CD4+ T cells." (PMID 37161048, 2023). "As intratumoral administration of CpG has been reported in previous study to increase OX40 expression on CD4+ lymphocytes in TME, meanwhile, there were also studies demonstrating that radiotherapy may induce OX40 expression on tumor infiltrating CD4+ T cells." (PMID 37700338, 2023).
tumor (continued). "Additionally, CD4+ T cells can also kill tumor cells by increasing the number and quality of B Cells and CTL (Cytotoxic T Lymphocytes) responses." (PMID 37274740, 2023). "However, CD3+CD8+ tumor-infiltrating T lymphocytes (TIL) correlate with better survival, whereas CD4+Foxp3+ TIL is associated with a poorer prognosis." (PMID 37444550, 2023). "Thus, mechanistic studies of tumor-mediated metabolism-rewiring in CD4+ T cells are relevant for uncovering novel therapeutic strategies." (PMID 38062068, 2023). "Although nude mice are useful model to assess tumor xenograft development because of athymic congenitally, extrathymic T cells including CD4 + or CD8 + cells could partially develop maturation as age growth in nude mice." (PMID 37880708, 2023). "Besides Treg depletion mechanism, the agonistic anti-OX40 can also inhibit tumor by augmenting activation and proliferation of CD4 +T cells that results into activation of CD8 +T cells." (PMID 37576888, 2023). "We speculate that the over-representation of CD4+Tmem cells expressing inhibitory receptors from adipose tissue of PC patients reflects tumour-driven T cell exhaustion." (PMID 37580610, 2023). "Existing study reveals that DNA damage repair and immunogenic tumor microenvironment in GC could be characterized by activated subsets of CD4 T cells." (PMID 38154092, 2023). "One explanation may lie with tumor macrophages and the regulation of cytokine production by CD4+ T cells." (PMID 38375204, 2023). "Indeed, flow cytometry validated that tumor-infiltrating CD4+ T cells from the Ythdf1-KO group exhibited strong production of IFN-γ and granzyme B." (PMID 36650153, 2023). "Therefore, accumulated MDSCs and the higher inflammasome activation co-ordinately induced more IL-17 production of naive CD4+ T cells, contributing to the impairment of tumour surveillance." (PMID 37916155, 2023). "Our results indicated that the expression of ORC1, ORC2, ORC3, ORC4, ORC5, and ORC6 was different in the seven common types of tumor‐infiltrating immune cells, such as B cells, CD4 T cells, CD8 T cells, NK cells, macrophages, endothelial cells, and cancer‐associated fibroblasts." (PMID 36205357, 2023). "Moreover, flow cytometry of freshly dissociated TILs from patients with a range of tumor types revealed similar expression patterns at the protein level on CD4+ and CD8+ T cells." (PMID 37593752, 2023). "Significantly, differences in TME composition such as number of CD4 + or CD8 + T cells are increased during on-treatment than before suggesting that predictive biomarkers based on immune signatures should be evaluated in on-treatment tumor samples." (PMID 38066522, 2023). "Therefore, IFN‐γ and TNF‐α secreted by CD4+ T cells play a synergistic role in the inhibition of angiogenesis in tumor tissue by cutting off the blood supply to solid tumors to reduce tumor survival and metastasis." (PMID 37829505, 2023). "The use of OIMH NPs in combination with α-PD-L1 (2.5 mg/kg) in a CT26 bilateral mice tumor model led to increased infiltration of CD4+ (18.9% and 33.4%) and CD8+ (36.7% and 35.1%) T cells in primary and distant tumors, respectively, resulting in greater tumor growth inhibition." (PMID 36987269, 2023). "In addition to phenotypic similarities, CD4 CTL subsets identified in our study also exhibit functional similarities to the anti-tumor T-cell populations detected in cancer patients." (PMID 37185301, 2023). "Notably, the combination of PD-L1 blockade and CD4+ T cell depletion induced tumor regression compared to the control group." (PMID 36969495, 2023). "Mice depleted of CD4+ T cells had a diminished ability to inhibit CT26 tumor growth." (PMID 37244905, 2023). "Myeloid cells and T cells were the most abundant cell types in tumors and normal lung tissues, while tumor-associated macrophage-folate receptor 2 (TAM-FOLR2) and CD4+ nuclear receptor subfamily 4 group A member 3 (NR4A3) exhibited sharp increases in invasive adenocarcinoma (IA)." (PMID 37532692, 2023).